IL13RA2 (interleukin 13 receptor subunit alpha 2)
Diseases named in the same sentence as IL13RA2 in open-access papers (continued):
Sharing a sentence is not in itself a finding about the gene and the disease.
lung carcinoma (10 papers, 2015 to 2025). "Gene–disease and gene–gene network analyses indicated that CHI3L1 and IL‐13Rα2 are commonly associated with many diseases including lung cancer and these genes are colocalized." (PMID 34758182, 2022). "(iii) IL13Rα2 overexpression was more frequently detected in lung adenocarcinoma and associated with poor prognosis in resected lung cancer patients." (PMID 26418721, 2015). "TAZ activation was found on IL13Rα2 transfected lung cancer cells and was associated with lung cancer invasion." (PMID 26418721, 2015). "CHI3L1 regulates the IL-13 signaling pathway through IL-13Rα2, leading to increased secretion of cytokines, such as IL-1β and IL-6, which can influence inflammation in lung cancer." (PMID 38177294, 2024). "The protein expression of CHI3L1, IL‐13Rα1, and IL‐13Rα2 was significantly higher in tumor tissues than in normal tissues of lung cancer patients." (PMID 34758182, 2022). "In conclusion, we reveal that IL13Rα2 promotes lung cancer growth, invasion and metastasis via the activating PI3K-TAZ pathway." (PMID 26418721, 2015). "In our model, IL13Rα2 signaling increased tumor invasion through PI3K activation, as PI3K inhibitor LY294002 blocked the effect of IL13Rα2 on lung cancer invasion." (PMID 26418721, 2015). "Here, we have described an important role for IL13Rα2 in lung cancer growth, invasion and metastasis." (PMID 26418721, 2015). "We examined the expression level of IL13Rα2 using western blotting in a panel of human lung cancer cells and normal lung epithelial cell lines." (PMID 26418721, 2015). "Collectively, these data indicate that IL13Rα2 promotes lung cancer progression through PI3K-TAZ pathway." (PMID 26418721, 2015). "Together, these results indicate that IL13Rα2 signaling requires PI3K to activate TAZ in lung cancer." (PMID 26418721, 2015). "In this study, we elucidated the role for PI3K in the signal transduction of IL13Rα2 for the invasion of lung cancer cells." (PMID 26418721, 2015). "The conclusion was obtained from the following observations: (i) IL13Rα2 increased lung cancer cells growth and anoikis resistance." (PMID 26418721, 2015). "This worse prognosis could be attributed to the increased invasive and metastatic ability of IL13Rα2 in lung cancer cells." (PMID 26418721, 2015). "We verified that IL13Rα2 activated TAZ to promote lung cancer invasion in vitro." (PMID 26418721, 2015). "Silencing of IL13Rα2 in lung cancer cells decreased invasion in vitro and lung metastasis in vivo." (PMID 26418721, 2015). "(ii) IL13Rα2 silencing suppressed lung cancer growth, invasion and metastasis." (PMID 26418721, 2015). "IL13Rα2 promoted the migration, invasion and anoikis resistance of lung cancer cells in vitro." (PMID 26418721, 2015). "IL13Rα2 expression was mainly associated to human lung cancer, while weak or no IL13Rα2 expression was found in adjacent normal lung tissues." (PMID 26418721, 2015). "We showed that IL13Rα2 overexpression was associated with late stages of disease progression and shorter disease-free survival (DFS) as well as overall survival (OS) in resected lung cancer patients." (PMID 26418721, 2015). "IL13Rα2 promoted lung cancer growth and invasion in vitro and in vivo." (PMID 26418721, 2015). "We suggest that inhibition of IL13Rα2 is a potential therapeutic approach in lung cancer." (PMID 26418721, 2015). "Our work is consistent with a recent study which indicated IL13Rα2 could be a biomarker for lung cancer especially lung adenocarcinoma." (PMID 26418721, 2015). "Taken together, these data strongly suggest that IL13Rα2 promote lung cancer growth and metastasis." (PMID 26418721, 2015). "Thus, it can be speculated that inhibition of the interaction between CHI3L1 and IL‐13Rα2 by K284 could prevent lung cancer cell metastasis and growth." (PMID 34758182, 2022). "Thus, inhibition of IL13Rα2 is a potential therapeutic approach in lung cancer." (PMID 26418721, 2015).
lung carcinoma (continued). "However, little was known about the role of IL13Rα2 during lung cancer progression." (PMID 26418721, 2015). "Non-coding RNA and IL-13 receptor subunit alpha-2 (IL13Rα2) which both involved in PI3K/AKT pathway regulation inhibit anoikis and result in lung carcinoma metastasis and grave prognosis." (PMID 37169018, 2023). "In our in vitro study, inhibitory effects of K284 on the binding of CHI3L1 to IL‐13Rα2 blocked JNK, AKT, and AP‐1 signaling and the expression of related genes (c‐Fos and c‐Jun) in cultured lung cancer cells." (PMID 34758182, 2022). "In the tissue samples from lung cancer patients, the protein expression of CHI3L1, IL‐13Rα1, and IL‐13Rα2 and the phosphorylated levels of c‐Jun, c‐Fos, AKT, and ERK were elevated compared with those in normal lung tissues." (PMID 34758182, 2022). "The results indicated that the protein expression of IL13Rα2 was higher in HTB-57, NCI-H1975, NCI-H1299 and A549 cells compared with the others lung cancer cells and normal lung epithelial cells." (PMID 26418721, 2015). "However, the role of IL13Rα2 in lung cancer remains unknown." (PMID 26418721, 2015). "SCAN-ACT identified 174 monospecific CAR-T targets in GBM, including several established GBM CAR-T targets such as CD276, EGFR, IL13RA2, ROBO1, as well as targets studied in different diseases like GPC2 in neuroblastoma, IL11RA in osteosarcoma, or DLL3 in lung cancer." (PMID 40814001, 2025). "Additionally, CHI3L1 targets IL-13Rα2, activating the PI3K/Akt pathway to increase lung cancer cell proliferation, migration, and invasion." (PMID 38177294, 2024). "We further demonstrated that IL13Rα2 increased PI3K and TAZ expression in lung cancer cells." (PMID 26418721, 2015).
prostate carcinoma (10 papers, 2015 to 2024). A carcinoma that arises from epithelial cells of the prostate gland. "Higher expression of IL-13Rα2 was also associated with castration resistance in prostate cancer cells." (PMID 39598436, 2024). "In conclusion, IL13Rα2 was highly expressed in a castration‐resistant prostate cancer PDX model and was associated with the castration resistance of prostate cancer cells." (PMID 36806727, 2023). "IL13Rα2 was highly expressed in castration‐resistant prostate cancer PDX models and was associated with the castration resistance of prostate cancer cells." (PMID 36806727, 2023). "In this study, we evaluated the function of IL13Rα2 associated with the castration resistance of prostate cancer and explored its clinical utility as a tissue and serum biomarker for predicting castration resistance in prostate cancer patients." (PMID 36806727, 2023). "In this study, our results have demonstrated altered expression of IL-13Rα2 in prostate cancer tissues and cell lines." (PMID 36830725, 2023). "The expression of IL-13Rα2 mRNA and protein in prostate cancer tissues and cell lines was assessed via real-time PCR (RT-PCR) and immunoblotting." (PMID 36830725, 2023). "By comparing the gene expression of these tumors, we explored biomarkers for predicting the castration resistance of prostate cancer and found that the α2 chain of interleukin‐13 receptor (IL13Rα2) was highly expressed in castration‐resistant models." (PMID 36806727, 2023). "IL-13Rα2 protein cell surface expression is relatively high in metastatic prostate cancer cell lines DU145 and PC-3 (59.6 ± 7.2-fold (p ≤ 0.001) and 93.8 ± 7.7-fold (p ≤ 0.001) overexpression in DU145 and PC-3, respectively, compared to PNT2)." (PMID 36830725, 2023). "Since IL-13Rα2 expression is relatively high in metastatic prostate cancer cells, we assessed in vitro the potential of Pep-1-Phor21 as a therapeutic drug for prostate cancer." (PMID 36830725, 2023). "It was reported that exogenous IL13Rα2 expression rendered prostate cancer cells sensitive to the cytotoxic therapy." (PMID 36806727, 2023). "The expression of the IL-13Rα2 gene was significantly higher in prostate cancer tissues than in normal prostate tissues." (PMID 36830725, 2023). "IL13RA2 mRNA was also more highly expressed in PC3 cells than in LNCaP cells, indicating that IL13Rα2 was highly expressed in castration‐resistant prostate cancer cells." (PMID 36806727, 2023). "Immunohistochemical analyses of IL13Rα2 were performed in prostate cancer tissues obtained at diagnosis of prostate cancer before patients had undergone any treatment." (PMID 36806727, 2023). "In our study, IL13Rα2 was highly expressed in castration‐resistant PDX tumors compared with castration‐sensitive tumors, indicating that the IL13Rα2 has a potential to predict the castration‐sensitivity of prostate cancer." (PMID 36806727, 2023). "The hybrid lytic peptide cytotoxic activity correlated with the expression of IL-13Rα2 in prostate cancer cell lines cultured as monolayers (2D) or 3D spheroids." (PMID 36830725, 2023). "Using the same methods, IL13Rα2 concentrations in serum samples of prostate cancer patients were measured." (PMID 36806727, 2023). "IL-13Rα2 mRNA expression was low but detectable in PNT2 cells and therefore IL-13Rα2 mRNA expression in PNT2 cells was used to compare with that in the prostate cancer cell lines to analyse relative expression." (PMID 36830725, 2023). "IL13Rα2 is a membranous protein and its expression levels in prostate cancer tissues can be evaluated by immunohistochemical analyses." (PMID 36806727, 2023). "Together, these results suggest that the expression pattern of IL-13Rα2 in 3D-cultured prostate cancer cell lines is similar to that observed in 2D-cultured cells." (PMID 36830725, 2023). "In this study, we have described a new peptide drug that specifically targets IL-13Rα2 on the surface of prostate cancer cell lines and thereby becomes toxic to these cells." (PMID 36830725, 2023).
prostate carcinoma (continued). "We have employed a lytic peptide Pep-1-Phor21 to target prostate cancer cell lines expressing IL-13Rα2." (PMID 36830725, 2023). "Together, these results suggest that IL-13Rα2 expression is high in prostate cancer tissues and metastatic cell lines." (PMID 36830725, 2023). "We found that the prostate cancer patients with higher expression of IL13Rα2 in biopsy tissues had a significantly shorter time to castration resistance after ADT." (PMID 36806727, 2023). "Similarly, we have also demonstrated that calcitonin gene related peptides (CGRPs) induce and upregulate expression of IL‐13Rα2 in prostate cancers in vitro and in vivo." (PMID 38685487, 2024). "As TSA or 5-aza-dC treatments increase IL-13Rα2 expression in prostate cancer cells, we determined whether treatment with these epigenetic modulators also altered the sensitivity of prostate cancer cells to Pep-1-Phor21." (PMID 36830725, 2023). "IL13Rα2 was higher in castration‐resistant prostate cancer PDX tumor and clinical samples." (PMID 36806727, 2023). "Studies have shown that IL-13Rα2 is overexpressed in prostate cancer cells, suggesting that it could be used both as a potential biomarker and also as a potentially important therapeutic target for preventing cancer progression." (PMID 36830725, 2023). "We also showed, in this study, that histone deacetylation and DNA methylation inhibitors upregulated IL-13Rα2 in prostate cancer cells, and went further to determine whether this would enhance the sensitivity of the cells to Pep-1-Phor21." (PMID 36830725, 2023). "Importantly, IL-13Rα2 mRNA expression levels in prostate cell lines correlated with levels in prostate cancer tissue samples and healthy tissue." (PMID 36830725, 2023). "The IL-13Rα2 cell surface receptor is highly expressed in tumours such as prostate cancer." (PMID 36830725, 2023). "Therefore, IL13Rα2 has been shown to be a promising target for cancer treatment including prostate cancer." (PMID 36806727, 2023). "Since TSA and 5-aza-dC treatment were shown to alter IL-13Rα2 expression in prostate cancer cells grown in 2D culture, we investigated whether the treatments could also alter the expression of IL-13Rα2 in prostate cells grown in 3D culture as cell spheroids." (PMID 36830725, 2023). "In addition, TSA or 5-Aza-dC treatment of prostate cancer cells, particularly those with low expression of IL-13Rα2, enhanced the cells’ sensitivity to the lytic peptide by increasing IL-13Rα2 expression." (PMID 36830725, 2023). "Some of the prostate cancer cells expressing IL13Rα2 might be escape from the castration therapy leading to castration resistance." (PMID 36806727, 2023). "As TSA and 5-aza-dC treatments increased IL-13Rα2 expression in prostate cancer cells grown in 3D culture, the effect of TSA or 5-aza-dC treatment on the sensitivity of prostate cancer cell spheroids to Pep-1-Phor21 was determined in vitro using the CellTox assay." (PMID 36830725, 2023). "IL-13Rα2 mRNA expression was observed in prostate cancer cells but was undetectable in PNT2 cells." (PMID 36830725, 2023). "Moreover, IL13Rα2 protein was highly expressed in aggressive and metastatic prostate cancer cells and antagonized IL‐13 function." (PMID 36806727, 2023). "Altogether, the data indicate that IL-13Rα2 is expressed in prostate cancer and could be used as a possible therapeutic target." (PMID 36830725, 2023). "On the basis of these results, it was suggested that the IL13Rα2 protein might protect prostate cancer cells specifically in a starved state under treatment with ADT." (PMID 36806727, 2023). "This was significantly higher in LNCaP‐IL13Rα2 than in LNCaP‐mock, indicating that IL13Rα2 protein secreted by the prostate cancer cells could be measured by ELISA." (PMID 36806727, 2023). "In serum samples, IL13Rα2 levels could be measured in 5 of 28 (18%) castration‐resistant prostate cancer patients." (PMID 36806727, 2023).
prostate carcinoma (continued). "To determine whether the expression of the IL-13Rα2 gene is altered in prostate cancer, we assessed IL-13Rα2 expression at the mRNA level in human prostate cancer tissues using the TissueScan prostate cancer cDNA array via RT-PCR." (PMID 36830725, 2023). "Besides, IL13RA2 is associated with several types of cancer progression, including the EMT of prostate cancer." (PMID 26114873, 2015). "In this report, we evaluated the hypothesis that prostate cancer cells with enhanced IL-13Rα2 expression are a suitable target for the hybrid lytic peptide (Pep-1-Phor21) peptide, which is generated by fusing the IL-13Rα2 specific ligand (Pep-1) and a cell membrane disrupting lytic peptide (Phor21)." (PMID 36830725, 2023). "The expression of IL-13Rα2 mRNA and protein was also further increased in DU145 and PC-3 cell lines after TSA or 5-aza-dC treatment, indicating that IL-13Rα2 expression is epigenetically regulated in prostate cancer cell lines." (PMID 36830725, 2023). "The expression of IL-13Rα2 was observed to be significantly higher in the metastatic prostate cancer cell lines DU145 and PC-3 than in either the non-cancerous prostate cell line PNT2 or the non-metastatic prostate cancer cell line LNCaP." (PMID 36830725, 2023). "Since the central layers of multicellular spheroids are hypoxic, the reduction in IL-13Rα2 expression in prostate cancer spheroids could be due to the lack of oxygen." (PMID 36830725, 2023). "Finally, we analysed IL-13Rα2 expression and sensitivity to Pep-1-Phor21 of 3D-cultured prostate cancer cells treated without or with epigenetic inhibitors." (PMID 36830725, 2023). "However, it was not elucidated whether the sequential changes of IL13Rα2 expression during the castration therapy was correlated with castration‐resistance of prostate cancer." (PMID 36806727, 2023).
pulmonary fibrosis (10 papers, 2010 to 2024). Chronic progressive interstitial lung disorder characterized by the replacement of the lung tissue by connective tissue, leading to progressive dyspnea, respiratory failure, or right heart failure. "On the other hand, IL-13Rα2 has a strong affinity for IL-13, and its activation is associated with the pathogenesis of various diseases, such as inflammatory bowel disease, dermatitis, and lung fibrosis." (PMID 39598436, 2024). "IL-13Ra2 has an anti-fibrotic effect, as its overexpression inhibits the expression of fibrotic markers in vitro and in pulmonary fibrosis in vivo." (PMID 36014018, 2022). "IL-13 is elevated after administration of bleomycin in murine lungs and enhanced IL-13Rα2 signaling is thought to be involved in bleomycin-induced lung fibrosis." (PMID 21067601, 2010). "Finally, we determined that therapeutic neutralization of IL-13, during the period of IL-13Rα2 saturation was sufficient to protect mice from lung fibrosis." (PMID 28004808, 2016). "The manner in which IL13-PE continues to work in the lung despite the presence of these neutralizing antibodies is not presently clear but we have observed that the numbers of IL-13Rα2-positive cells during pulmonary fibrosis are markedly increased (and unpublished findings)." (PMID 20090941, 2010). "Furthermore, IL-13Rα2-mediated regulation of TGF-β expression in a lung fibrosis model suggests that IL-13Rα2 may play a role in the invasion and metastatic potential of cancers through the epithelial-to-mesenchymal transition (EMT) process." (PMID 39598436, 2024). "Previous studies have found that IL-13 signals through IL-13R2 to induce transforming growth factor beta (TGF-β) and fibrosis progression, and silencing of IL-13Rα2 reduced TGF-β production and lung fibrosis." (PMID 36685820, 2022). "Il13ra2 gene silencing or blockade of IL-13Rα2 signaling led to marked downregulation of TGF-β1 production and collagen deposition in a model of lung fibrosis." (PMID 31866859, 2019). "The suppression of IL-13Rα2 expression, the receptor of IL-13 involved in TGF-β signaling, by loading small interfering RNA (siRNA) to IL-13Rα2 in HVJ-envelope vectors led to the neutralization of bleomycin-induced pulmonary fibrosis and retardation of collagen deposition." (PMID 36499287, 2022).